MTOR (mechanistic target of rapamycin kinase)
Diseases named in the same sentence as MTOR in open-access papers (continued):
Sharing a sentence is not in itself a finding about the gene and the disease.
tumor (continued). "The effect of Rapamycin on the mTOR pathway was further examined in short-term primary cultures of Wnt-1 tumor cells and in two clonal cell lines established from these tumors." (PMID 18570671, 2008). "Tumours that coexpressed caveolin-1 and activated mTOR components were more likely to be larger, higher grade and to show vascular invasion." (PMID 18283322, 2008). "As a similar (∼80%) and significant reduction of EGFR and mTOR occurred after combination therapy, it is most likely that this dual suppression is a key mechanistic component of the observed tumour suppression." (PMID 18797454, 2008). "Several published papers showed that rapamycin played key role in inhibiting tumor proliferation by targeting mTOR and had synergistic anti-tumors effects with some chemotherapeutic drugs such as arsenic trioxide in several kinds of tumors." (PMID 19115995, 2008). "The only aspects of the model that were modified during the simulations were activity-levels reflecting the immediate effects of either the underlying tumor mutations (Ras and PTEN) or the perturbations (mTOR-Raptor and TSC2 targeted manipulation)." (PMID 18463702, 2008). "To determine the functional significance of AMPK phosphorylation in CT-2A tumor cells and astrocytes, we examined the mTOR/S6K protein synthesis pathway." (PMID 18474106, 2008). "To address this, we examined the coexpression of caveolin-1 and phosphorylated mTOR (pmTOR) pathway components in tumour tissue from 174 RCC patients presenting with localised disease." (PMID 18283322, 2008). "In this study, we stressed that some tumour types with abnormalities involving the PI3K/AKT/mTOR pathway or with sustained antiangiogenic activity such as kidney cancers are highly sensitive to mTORC1 inhibitors." (PMID 18797463, 2008). "Rapamycin (sirolimus) is an antifungal antibiotic possessing immunosuppressive and anti-tumor activity by inhibiting the mTOR pathway." (PMID 18570671, 2008). "Only pS6 from the AKT/mTOR pathway predicted a reduced disease-free survival, although when cross tabulated with all other known prognostic determinants pS6 correlated with tumour grade only." (PMID 18283322, 2008). "Phosphorylated mTOR correlated with tumour size (P=0.023), capsular invasion (P=0.015) and with papillary tumour type (P=0.006)." (PMID 18283322, 2008). "The PI3K pathway was found to be activated in BLCs and up-regulated compared with HER2+ tumours as shown by a significantly increased activation of the downstream targets Akt and mTOR (mammalian target of rapamycin)." (PMID 19055754, 2008). "Activity of mTORC1 inhibitors, particularly temsirolimus, in renal cell cancer has raised the possibility that responders share a common molecular phenotype that renders these tumours dependent on mTOR for growth and/or survival." (PMID 18797463, 2008). "mTOR inhibitors have anti-neoplastic potential since mutations in LKB1, TSC2, or PTEN tumor suppressor genes produce aberrant mTOR activation in certain neoplastic conditions." (PMID 18474106, 2008). "Further work suggested that feedback down-regulation of receptor tyrosine kinase signaling is a frequent event in tumor cells with constitutive mTOR activation." (PMID 19384426, 2007). "We have shown previously that progressive tumor growth occurs even though the mTOR pathway is inhibited (as demonstrated by reduced pS6)." (PMID 17986349, 2007). "Enhanced tumor growth caused by constitutive activation of Akt in PTEN (-/-) cells also was reversed by CCI-779 (rapamycin derivative) treatment, indicating that mTOR functions downstream of Akt in tumorigenesis." (PMID 19384426, 2007). "It was also shown that in different tumor cell backgrounds inhibition of mTOR was less effective in inducing caspase-3 activity than inhibition of Akt1 and Akt2." (PMID 19384426, 2007). "A recent study in SCC cell lines demonstrates that inhibition of mTOR induces activation of Akt and results in antitumor effects in this tumour type." (PMID 17342092, 2007).
tumor (continued). "Rapamycins are highly specific inhibitors of mTOR and potently suppress tumour cell growth by retarding cells in G1 phase or potentially inducing apoptosis." (PMID 16953237, 2006). "Anecdotally, in many cell lines and patient tumour biopsies, inhibition of mTOR activates Akt and inhibits downstream substrates (FoxO transcription factors, Bad, and GSK3α/β)." (PMID 16953237, 2006). "Pharmacodynamic analysis in paired tumour biopsies reflected effective mTOR pathway downregulation and identified possible predictive factors." (PMID 17031397, 2006). "There is strong evidence that up regulation of HIF by mTOR is a frequent mechanism regulating tumor growth." (PMID 16412252, 2006). "Notably, palmitoylation of tumor intrinsic PD-1 activates mTOR signaling and promotes tumor cell proliferation." (PMID 41486149, 2026). "Given the critical role of autophagic regulation in controlling tumor immune evasion and cell death, the present study investigates the effects of BCc1 on key autophagy-associated genes ATG-4B, ATG-7, Beclin-1 and the mTOR signaling pathway using a BALB/c mouse model of BC." (PMID 41550506, 2026). "Combined inhibition of HSP27 using the antisense oligonucleotide OGX-427 (Apatorsen) and mTOR blockade via Sapanisertib induced a robust synergistic anti-tumor effect across diverse preclinical models, including advanced PC Patient-derived organoid (PDOs) and CRPC xenografts." (PMID 41877198, 2026). "Notably, this study represents the first global exploration of BCc1 nanomedicine's potential to induce autophagy, a process mediated by autophagy-related genes (Beclin-1, ATG-4B, ATG-7, and mTOR), while evaluating tumor cell death." (PMID 41550506, 2026). "Dual PI3K/mTOR inhibitors such as gedatolisib have shown clinical promise, but they still face challenges, including low solubility, poor metabolic stability, and limited activity against resistant tumor phenotypes." (PMID 41726721, 2026). "Functionally, BCc1-mediated mTOR inhibition carries significant implications for tumor suppression." (PMID 41550506, 2026). "Consequently, CMSP suppresses autophagy in ESCC cells by reducing lysosomal acidification and the AMPK/mTOR pathway, ultimately triggering apoptosis in tumor cells." (PMID 41531896, 2026). "Finally, in vivo xenograft studies demonstrated that NDUFA9 silencing suppressed tumor growth, corroborating the in vitro findings by inhibiting mitochondrial function, proliferation, Akt-mTOR activation, and inducing apoptosis within tumor tissues." (PMID 42014681, 2026). "By attenuating mTOR activity, BCc1 may impede tumor growth, restrict angiogenic signaling, and enhance tumor responsiveness to immunotherapeutic interventions, including checkpoint blockade." (PMID 41550506, 2026). "18F-FDG uptake is closely associated with several key tumor processes, including glucose metabolism (mediated by GLUT1 and hexokinase I), hypoxia response (via HIF-1α), angiogenesis (driven by VEGF and CD34), and the PI3K/Akt/mTOR signaling pathway, which promotes tumor invasiveness." (PMID 40699302, 2026). "The differential magnitude of mTOR suppression between BCc1 and cyclophosphamide also provides a mechanistic rationale for combination regimens, potentially enabling synergistic inhibition of tumor growth while mitigating adaptive resistance." (PMID 41550506, 2026). "Because the PI3K/AKT and AMPK/mTOR signaling pathways are classical pathways involved in energy metabolism, we next analyzed tumor samples from the TCGA database and found that patients with high expression of ENO1 (a key enzyme in glycolysis) presented higher glycolysis-related scores." (PMID 41168198, 2025).
tumor (continued). "Dysregulation of insulin signaling can activate the PI3K/Akt/mTOR and Ras/Raf/MAPK pathways, which may enhance cell proliferation and increase the risk of neoplasia in the breast." (PMID 41463284, 2025). "Overall, advanced transcriptomic technologies have significantly enhanced our understanding of fibroid pathogenesis, shedding light on crucial pathways such as ERK1/ERK2, mTOR, and collagen signaling, as well as the roles of specific cell populations in tumor progression." (PMID 39936948, 2025). "AIM2 has been shown to impede the malignant behaviors of CRC cells, such as proliferation and migration, through modulation of the AKT/mTOR signaling pathway, NF-κB signaling pathway, Notch signaling pathway, mitochondrial dynamics, and cell cycle regulation, thereby exhibiting anti-tumor effects." (PMID 39744568, 2025). "The Akt/mTOR pathway, an important tumor-related pathway, could be inhibited by TVB3664 and AZ12756122, which ultimately suppressed the growth of HCC and NSCLC." (PMID 40868150, 2025). "Attempts to apply mTOR inhibitor monotherapy to other tumor types have been less successful." (PMID 40094009, 2025). "In addition to directly controlling the energy metabolism of tumor cells, the mTOR signaling pathway also controls immune cell activity, which has synergistic anti-tumor effects." (PMID 41451233, 2025). "Rho GTPase-activating protein 25 (ARHGAP25) acts as a tumor suppressor by inhibiting the AKT/mTOR signaling pathway, and may provide a therapeutic target for PDAC." (PMID 40630951, 2025). "DDIT4-mediated autophagy activation through PI3K-Akt/mTOR pathway inhibition in tumor cells potentially regulates the expression of MHC-I molecules and immune checkpoint proteins, suggesting a critical link between cellular stress responses and tumor immunogenicity." (PMID 40900790, 2025). "Notably, IGF-1/PI3K/AKT/mTOR signalling participates in this metabolic reprogramming in hypertrophic cells, similarly to that in tumour processes." (PMID 39904372, 2025). "Overall, the inhibitory activity of culicinin D on tumor cell growth might be achieved by inhibiting the mTOR signaling pathway." (PMID 40429170, 2025). "A mechanistic exploration revealed that FBP1 increases FBXW7 protein levels by inhibiting the auto-ubiquitination of FBXW7, which promotes mTOR ubiquitination to inhibit mTOR levels, thereby inhibiting glycolysis and enhancing the anti-tumor effects of radiation." (PMID 40100307, 2025). "Furthermore, activated AKT can elevate HIF-1α protein levels via mTOR, enhancing anaerobic glycolysis in tumor cells and thereby promoting tumor growth." (PMID 41463642, 2025). "The introduction of mTOR inhibitors (mTORis), such as sirolimus and everolimus, has provided new insights into the management of the tumor-related forms of TSC, significantly improving patient quality of life by controlling tumor growth and reducing systemic complications." (PMID 40141713, 2025). "Overall, we concluded that ENO1 synergistically regulated the PI3K/AKT and AMPK/mTOR pathways through direct stimulation of glycolytic products and influenced the ATP pool and lactate homeostasis, ultimately promoting the stemness and tumor growth of GCs." (PMID 41168198, 2025). "The metformin-activated AMPK signaling pathway has been reported to inhibit tumor cell growth via inhibiting mTOR 86, which could be applied to Treg cells." (PMID 39776799, 2025).
tumor (continued). "However, in many tumour cells, overactivation of the PI3K/Akt/mTOR signalling pathway enables tumour cells to evade apoptosis and thus proliferate indefinitely." (PMID 40421249, 2025). "In state 6, the high expression of the PI3K/AKT/mTOR pathway coupled with low expression of Toll-like receptors may lead to abnormal tumour proliferation and immune escape, thereby limiting the effectiveness of immunotherapy." (PMID 40429821, 2025). "Besides, dysregulated signaling pathways like Wnt/β-catenin, NF-κB, and PI3K/AKT/mTOR contribute to tumor progression and resistance to treatment, highlighting the urgent need for more effective and targeted therapies." (PMID 40312353, 2025). "Additionally, we reveal that an mTOR inhibitor can increase tumor cell sensitivity to radiation-induced damage by downregulating GSTK1 expression, thereby weakening glutathione-mediated ROS clearance." (PMID 40963930, 2025). "Mutations in the EGFR gene, such as the EGFRvIII variant, lead to constant receptor activation and downstream signaling through the phosphatidylinositol-3-kinase (PI3K)/mammalian target of rapamycin (mTOR) pathway, promoting tumor growth and therapy resistance." (PMID 40650170, 2025). "mTOR inhibitor, such as rapamycin, could reduce NF‐λB activity, suppress inflammatory SASPs at the translational level, and constrain the tumor‐prompting effect of senescent bystander fibroblasts." (PMID 39811803, 2025). "Particularly, highly phosphorylated RPS6KB1 (p-RPS6) and RPS6 (p-RPS6) were linked to noticeably lower overall survival rates, suggesting that mTOR pathway activation might be involved in tumor aggressiveness." (PMID 40002868, 2025). "Furthermore, 5-HT activates the PI3K/Akt/mTOR signaling pathway, which further facilitates metabolic reprogramming and immune evasion in the tumor context." (PMID 40666095, 2025). "The relationship between mTOR and multiple stressors and effectors characterizes the conserved function of mTOR within stress responses as well as its universal function in a wide range of tumor types, leading to the issue of editing mTOR for strengthening NOA." (PMID 40183103, 2025). "Inhibition of the mTOR signaling pathway in tumor cells leads to apoptosis and lethal autophagy." (PMID 38735913, 2025). "Additionally, feedback loops exist wherein STAT3 upregulates components that further amplify mTOR signaling, thereby promoting tumor progression." (PMID 40806360, 2025). "Thus, combination treatment induced significantly greater tumor growth inhibition than either [177Lu]Lu-DOTA-CCK2R-dimer or the mTOR inhibitor alone." (PMID 40963930, 2025). "However, the role played by the PI3K/AKT/mTOR pathway in the process of tumor drug resistance due to FAO dysregulation is still unclear." (PMID 40514365, 2025). "Studies have shown that by regulating the AKT/mTOR signaling pathway, the expression levels of key enzymes in the glycolysis pathway can be inhibited, thereby reducing the energy supply of tumor cells, leading to the inhibition of tumor cell proliferation and even the death of tumor cells." (PMID 39910045, 2025). "Additionally, the pretreatment of 740Y‐P can remarkably overturn the effect of quercetin on inhibiting the PI3K/Akt/mTOR pathway, which can enhance tumor cell proliferation and inhibit cell apoptosis." (PMID 40347062, 2025). "In glioma models, mPEG-PCL nanoparticles (~135 nm) co-loaded with resveratrol and temozolomide acted synergistically by inhibiting the PI3K/Akt/mTOR signaling pathway, increasing pro-apoptotic protein expression, and delaying tumor progression in U87 xenograft mice." (PMID 40572668, 2025). "In BC organoids, the HER2 signaling pathway is typically aberrantly activated through heterodimerization with other HER family members, activating downstream pathways such as Ras/Raf/MEK/ERK and PI3K/AKT/mTOR, which promotes tumor cell proliferation, migration, and invasion." (PMID 41359105, 2025).
tumor (continued). "In tumour cells, overexpression of death-associated protein kinase 1 (DAPK1) mediated the disruption of the interaction between tuberous sclerosis complex proteins 1 and 2 (TSC-1/TSC-2), resulting in the activation of the mTOR pathway." (PMID 39904372, 2025). "CircLIPH may exert its oncogenic biological effects by activating the miR769-3p/GOLM1/PI3K/AKT/mTOR axis, whereas si-circLIPH effectively inhibited the expression of circLIPH and suppressed tumor growth through apoptosis in vivo." (PMID 40630951, 2025). "In addition, it has been shown that in breast cancer driven by cMYC amplification, combination of MYC plus mTOR inhibitors (AZD8055) synergized to suppress tumor growth in vivo." (PMID 40075567, 2025). "It inhibits tumor growth via an mTOR/AMPK-dependent pathway in cell cultures, mice, and humans." (PMID 41295303, 2025). "The PI3K/Akt/mTOR signaling pathway also plays a significant role in tumor relapse." (PMID 39934876, 2025). "Regarding other significant prognostic factors in our study cohort, pretreatment with mTOR-inhibitors might be an indirect sign of a higher tumor proliferation rate or of a pancreatic primary." (PMID 40148509, 2025). "The PI3K/AKT/mTOR signaling mediates the processes of tumor proliferation, invasion and metastasis." (PMID 40771929, 2025). "In HLC, DEG associated with the LTR vector were 7-fold that of the SIN vector, with upregulation of several oncogenes and tumour suppressor genes and pathways mainly associated with tyrosine kinase signalling, protein phosphorylation and other ERK1/2 cascade and P13K/AKT/mTOR related pathways." (PMID 40664913, 2025). "While mTOR inhibition did not lead to reductions in pNF tumor volume, patients with NF1-associated LGGs experienced either tumor shrinkage or stabilization, with minimal side effects." (PMID 41294711, 2025). "This suggests that ERP44-overexpressing tumor cells might possess enhanced survival mechanisms that bypass mTOR dependence, potentially related to its roles in ER stress adaptation or calcium signaling." (PMID 41049606, 2025). "Since the mTOR signaling pathway is closely related to tumor metabolism, this provides theoretical support for the combined application of mTOR inhibitors and drugs that interfere with tumor metabolism." (PMID 40944200, 2025). "We hypothesise that dual targeting of Hh and HER2 signalling pathways synergistically enhances anti-tumour effects by suppressing AKT/mTOR-driven proliferation and survival." (PMID 40426308, 2025). "The phosphoinositide 3‐kinase (PI3K)/protein kinase B (PKB or AKT)/mammalian target of rapamycin (mTOR) signaling pathway (commonly referred to as the PAM signaling pathway) plays a critical role in regulating tumor cell growth, proliferation, survival, angiogenesis, and related processes." (PMID 40206206, 2025). "An antibody targeting the C-terminus of HSPA5 has been shown to suppress the proliferation of GBM cells and induce apoptosis by inhibiting the PI3K/AKT/mTOR signaling pathway in vitro, and to delay tumor growth in a heterotopic tumor mouse model when combined with ionizing radiation." (PMID 41002413, 2025). "Furthermore, OGN’s tumor suppressor activity in BC is demonstrated to be mediated by its effect on the PI3K/AKT/mTOR pathways." (PMID 40051609, 2025). "Mechanistically, MRPL21 upregulated mitochondrial oxidative phosphorylation (OXPHOS) and increased PARylation level, inhibited autophagy through activating the downstream PI3K/AKT/mTOR signaling pathway, and ultimately led to tumor progression and cisplatin resistance in HNSCC." (PMID 40713706, 2025). "It inhibits pro-tumorigenic signals such as PI3K/Akt/mTOR and NF-κB, while activating tumor-suppressive pathways like AMPK, forming an intricate regulatory network that highlights its unique advantages and tremendous potential as a natural multi-target metabolic modulator." (PMID 41515171, 2025).